HMGB1 (high mobility group box 1)
Diseases named in the same sentence as HMGB1 in open-access papers (continued):
Sharing a sentence is not in itself a finding about the gene and the disease.
epilepsy (continued). "It has been proven that the HMGB1 level rises after four hours of drug-resistant epilepsy seizure events, making HMGB1 a promising marker for epilepsy." (PMID 37239204, 2023). "For example, the protein of the high mobility group B1 (HMGB1) has shown elevated expression and an increased proportion of translocation from the nucleus to the cytoplasm in patients with epilepsy." (PMID 37539386, 2023). "The neuroimmune inflammatory response mediated by IL-1β/IL-1R1 and HMGB1/TLR4 signaling pathways plays an important role in the pathogenesis of epilepsy." (PMID 37305762, 2023). "In other studies, rat anti-HMGB1 mAb inhibited the pathogenesis of epilepsy by preventing BBB permeability and inhibited the inflammatory process in pilocarpine-induced epilepsy." (PMID 36230933, 2022). "A study reported the therapeutic effect of anti-HMGB1 mAb on epilepsy start from 1 h and last to 24 h, indicating that there’s a potential clinical epilepsy treatment." (PMID 36310854, 2022). "HMGB1 is mainly involved in the pathophysiology of epilepsy by interacting with the primary receptor TLR4." (PMID 35837232, 2022). "HMGB1, IL-1β, and S-100B can be molecular markers in the incidence of epilepsy characterized by changes in serum concentrations so that they have clinical significance in the epileptic process and can predict outcomes." (PMID 36310854, 2022). "Animals with active epilepsy have elevated blood levels of HMGB1 compared to healthy or well-controlled individuals." (PMID 36388178, 2022). "An early expression of the inflammatory, pathologic disulfide isoform of HMGB1 indicates the likelihood of experiencing further seizures in patients with newly diagnosed epilepsy." (PMID 35837232, 2022). "High Mobility Group Box 1 (HMGB1) as an initiator and amplifier of the neuroinflammation is responsible for the onset and progression of epilepsy by overexpressing P-glycoprotein on the blood brain barrier." (PMID 36310854, 2022). "The goal of this review is to evaluate the prospects of anti-HMGB1 monoclonal antibodies in downregulating P-glycoprotein as a therapeutic approach in epilepsy management." (PMID 36310854, 2022). "Both miR-129-5p and miR-542-3p inhibit the development of epilepsy by suppressing HMGB1 expression and inhibiting the TLR4/NF-kB signaling pathway." (PMID 35837232, 2022). "Animal studies have found that translocation and release of HMGB1 occur in pathological foci of different types of epilepsy." (PMID 36388178, 2022). "In conclusion, HMGB1 can be used as a potential biomarker to predict epilepsy recurrence and prognosis." (PMID 36388178, 2022). "HMGB1 is a molecule that plays an important role in increasing BBB permeability in the acute phase of epilepsy." (PMID 36310854, 2022). "A clinical study suggested that increased HMGB1 or TLR4 expression correlated with a higher risk and severity of epilepsy, as well as the increased possibility of anti-seizure medication resistance." (PMID 35837232, 2022). "A study (2018) showed that the HMGB1/TLR4/NF-κB pathway mediates the activation of microglia in epilepsy." (PMID 35656438, 2022). "These receptors can be activated by DAMPs, such as High Mobility Group Box 1 (HMGB-1), as observed in epilepsy, and beta-amyloid plaques and alpha-synuclein, in Alzheimer’s and Parkinson’s disease, respectively." (PMID 35859905, 2022). "Some evidence shows that neuroinflammation contributes to the onset and progression of epilepsy alongside HMGB1 as an initiator and amplifier of the process." (PMID 36310854, 2022). "In epilepsy patients, HMGB1 is known to mediate microglia activation and pro-inflammatory cytokine production via the TLR4/NF-κB pathway." (PMID 34830412, 2021). "Studies have shown that there is an increase in the level of HMGB1 within 3-4h after drug-resistant epilepsy." (PMID 34221552, 2021). "This investigation supports that the HMGB1/TLR-4 axis is contributing toward seizure mechanisms during epilepsy." (PMID 34354662, 2021).
epilepsy (continued). "HMGB1 translocation in neurons led to decreased HMGB1 levels in the brain and increased HMGB1 levels in the plasma of pilocarpine-induced epilepsy rats." (PMID 33921725, 2021). "The therapeutic potential of anti-HMGB1 mAb has been recently reviewed in several HMGB1-mediated diseases including PD, epilepsy, TBI, and AD." (PMID 32046119, 2020). "HMGB1 was also found to be elevated in models of traumatic brain injury, neuroinflammation, epilepsy, and cognitive dysfunction." (PMID 33214598, 2020). "In the quest of exploring potential therapeutic strategy against epilepsy, HMGB1 has emerged as an promising target against epilepsy." (PMID 33732146, 2020). "High‐mobility group box 1 (HMGB1) is a key mediator of neuroinflammation and there are increased HMGB1 levels in laboratory animal models of epilepsy and human patients with epilepsy." (PMID 33150666, 2020). "The cutoff value for serum HMGB1 concentration was determined as 0.15 ng/mL, as it exhibited the highest sensitivity (82.1%) and specificity (65.4%) for predicting canine epilepsy." (PMID 33150666, 2020). "It was recently confirmed that the expression of TLR‐4 signaling cascade including HMGB1 was higher in the brain tissue of dogs with epilepsy than in normal dogs." (PMID 33150666, 2020). "Additional experiments should clarify the role of HMGB-1 in epilepsy patients and also analyze different isoforms." (PMID 32581999, 2020). "It was also demonstrated that superfusion of anti-HMGB1 mAb on the surface of brain slices derived from patients with repeated epilepsy inhibited epileptiform activity in the brain slices." (PMID 33321691, 2020). "HMGB1 neutralization strategy in a diverse range of HMGB1-mediated pathologies such as Epilepsy, MS, Traumatic brain injury (TBI) and cognitive decline has been well reported." (PMID 33732146, 2020). "This study aimed to establish preliminary support for the use of serum HMGB1 concentration as a potential biomarker for epilepsy in dogs." (PMID 33150666, 2020). "Earlier finding reported increased mRNA expression of HMGB1 in a pilocarpine-induced epilepsy model in mouse." (PMID 32260203, 2020). "Results of the present study are in line with a previous report about human patients with epilepsy showing higher serum HMGB1 concentration in the epilepsy group than in the healthy control group." (PMID 33150666, 2020). "Regarding idiopathic epilepsy, dogs with an epilepsy course of >3 months showed a higher serum HMGB1 concentration (median = 0.87 ng/mL; range, 0.42‐2.88) than those with that of ≤3 months (median = 0.26 ng/mL; range, 0.03‐0.88; P = .02)." (PMID 33150666, 2020). "Upregulated mRNA expression of HMGB1 has been observed in a Pilocarpine induced epilepsy model in mice and in seizure model in adult zebrafish." (PMID 33732146, 2020). "Elevated HMGB1 has been reported in brain tissue resected from patients with epilepsy, while inhibition of HMGB1 in animal models has been found to reduce seizure pathology and the development of epilepsy in acquired epilepsy models." (PMID 31717556, 2019). "The level of HMGB1 has been shown to increase within 3–4 h after a drug-resistant epilepsy (DRE) seizure, proving HMGB1 to be a promising marker." (PMID 31312171, 2019). "Both serum HMGB1 (P<0.001) and TLR4 (P<0.001) expressions were higher in epilepsy patients than in HCs, and they displayed good predictive values for risk of epilepsy." (PMID 31241711, 2019). "In conclusion, both HMGB1 and TLR4 expressions were correlated with increased risk and severity of epilepsy and their level was higher in patients resistant to anti-epilepsy drugs." (PMID 31241711, 2019). "In conclusion, both increased HMGB1 and TLR4 expressions correlated with higher risk and severity of epilepsy as well as the elevated possibility of anti-epilepsy drug resistance." (PMID 31241711, 2019).
epilepsy (continued). "This study aimed to investigate the association of serum high-mobility group box-1 (HMGB1) and toll-like receptor 4 (TLR4) expressions with the risk of epilepsy as well as their correlations with disease severity and resistance to anti-epilepsy drugs." (PMID 31241711, 2019). "Only a few clinical studies have been performed to explore roles of HMGB1 and TRL4 expressions in risk and severity of epilepsy seizures." (PMID 31241711, 2019). "Taking together our present results with the available previous published data, HMGB-1 and its receptors emerge as a tempting pathway to target in order to change the development of epileptogenesis and probably the natural history of epilepsy as a disease." (PMID 31507379, 2019). "Taken together, our results show that HMGB-1 has distinct effects on the different CNS cell types, in the context of the early stages following a typical acute precipitating injury in epilepsy." (PMID 31507379, 2019). "The authors suggested that HMGB1 can be a prognostic factor of the frequency of seizures in the course of epilepsy." (PMID 31312171, 2019). "In contrast, while the modulation of HMGB1 has been postulated to have anti-ictogenic activity in experimental epilepsy models inhibition via glycyrrhizin in the same TBI model did not alter seizure outcomes." (PMID 31717556, 2019). "To further investigate the effect of HMGB1 in epilepsy patients, we divided patients into different subgroups according to disease status, disease course, seizure duration, and seizure frequency." (PMID 31241711, 2019). "Studies on experimental models of epilepsy suggest that the acetylated, disulfide form of HMGB1 determines the detrimental effects of inflammation in epilepsy." (PMID 31156384, 2019). "To remain consistent with our ongoing work that investigates the correlation between MRI data in HMGB1 in people with epilepsy, we will use an identical approach of data acquisition and analysis." (PMID 31619436, 2019). "We have soon-to-be-published data suggesting that molecular isoforms of high mobility group Box 1 (HMGB1) – a protein critically involved in the initiation of the inflammatory cascade in epilepsy –17 have potential as a prognostic biomarker." (PMID 31619436, 2019). "It has been shown that miRNA-129-5p plays a role in the inhibition of the development of autoimmune encephalomyelitis-related epilepsy rat model by targeting HMGB1." (PMID 31312171, 2019). "HMGB1 expression in patients with intractable epilepsy was significantly higher than that in patients with drug-responsive epilepsy (P=0.002)." (PMID 31241711, 2019). "In spite of its proven role in TBI, neuroinflammation, epilepsy and cognitive decline there has been little interest in exploring HMGB1 as a common target and biomarker for those conditions." (PMID 30271319, 2018). "There is mounting evidence which report that neuroinflammatory processes in the pathophysiology of seizures/epilepsy and HMGB1 were found to behave like an inflammatory cytokine in response to epileptogenic insults." (PMID 30271319, 2018). "Limited data is available regarding evaluation of therapeutic benefits of HMGB1 inhibitors in animal models of epilepsy." (PMID 30271319, 2018). "Pharmacological and genetic studies on animal and clinical brain specimens showed that translocation and release of HMGB1 occurs in the pathological epileptogenic focus of different type of epilepsy." (PMID 30271319, 2018). "MicroRNA-129-5p inhibited the development of autoimmune encephalomyelitis (AE)-related epilepsy by HMGB1 expression and inhibiting the TLR4/NF-κB signaling pathway." (PMID 30271319, 2018). "Earlier study recommended HMGB1 isoforms as a mechanistic biomarkers for epileptogenesis where they investigate the value of blood HMGB1 in predicting epilepsy development as well as differentiating epileptogenic from non-epileptogenic rats after SE." (PMID 30271319, 2018).
epilepsy (continued). "The therapeutic benefits of anti-HMGB1 mAb on epilepsy have been previously demonstrated in animal model of epilepsy." (PMID 30271319, 2018). "Several studies were previously conducted to determine the involvement of HMGB1 in the pathogenesis of epilepsy." (PMID 30271319, 2018). "Recent investigation shed more light on multiple roles of HMGB1 in a diverse range of pathologies such as brain injury, epilepsy, and neuroinflammation and cognitive decline." (PMID 30271319, 2018). "The expression level of HMGB1 was significantly elevated in the hippocampus and cortex after 24-h in a KA-induced model of SE, which suggests that the HMGB1 protein has a key role in epilepsy." (PMID 30271319, 2018). "In other words, it is likely that HMGB1 mediates the recurrence and progression of epilepsy through the damage of BBB and induction of inflammation." (PMID 28446773, 2017). "Experimental evidence from an animal model of temporal lobe epilepsy suggests that HMGB1 contributes to seizure activity and epilepsy." (PMID 28086980, 2017). "Previous studies mostly focused on the pro-inflammatory and pro-convulsant effects of HMGB1 in the pathological process of epilepsy, while the present study firstly demonstrates the important role of HMGB1 in seizure-induced overexpression of P-gp." (PMID 26485677, 2015). "Strong evidence supporting such a signaling event by HMGB1 was discovered by Maroso and colleagues in a chronic epilepsy model." (PMID 22824385, 2012). "High mobility group box 1 protein (HMGB-1) has recently gained significant attention for its role in initiating neuronal hyperexcitability, modulating neuroinflammation, and influencing cognitive function in epilepsy." (PMID 40894200, 2025). "Many studies have reported increased levels of HMGB1 in patients with epilepsy." (PMID 41155637, 2025). "However, the group with the highest activation of the HMGB1/TLR4/RAGE/NF‐κB pathway was the epilepsy group in this study." (PMID 39046369, 2024). "miR-149 may reduce the occurrence of epilepsy by inhibiting HMGB1-mediated neuroinflammatory injury." (PMID 39876842, 2024). "In many epilepsy models, HMGB1 was found to be high in both clinical and preclinical studies." (PMID 39046369, 2024). "Focal epilepsies can be treated by targeting miR-29a-HMGB1-IFN-γ." (PMID 39259090, 2024). "This suggests that HMGB1 serum concentration may be involved in the initiation and progression of epilepsy or epileptic lesions and is a potential predictive factor for epilepsy prognosis." (PMID 39046369, 2024). "Activated caspase-3 and DNA-binding protein HMGB1 can rapidly transfer to mitochondria and degrade mitochondrial proteins, thereby mediating the loss of hippocampal CA1 and GABAergic interneurons to maintain sustained epilepsy." (PMID 39876842, 2024). "This study aims to investigate the relationship between toxoplasmosis and this pathway, which may be effective in the formation of epilepsy by acting through the HMGB1/RAGE/TLR4/NF‐κB signalling pathway in patients with idiopathic epilepsy." (PMID 39046369, 2024). "Consistent with our results, HMGB1 was reported to be upregulated in both animal models of epilepsy and epileptic patients, suggesting miRNA-mediated suppression of HMGB1 expression as a potential therapeutic strategy for SE-associated neuroinflammation and neurodegeneration." (PMID 38332381, 2024). "HMGB1 binds to the TLR4 receptor in the epilepsy group and activates the inflammatory pathway." (PMID 39046369, 2024). "The signalling pathway in epilepsy may be activated by HMGB1, TLR4 and TLR2, which is considered to increase the level of proinflammatory cytokines." (PMID 39046369, 2024). "After the onset of epilepsy, the total serum concentration of HMGB1 increases significantly and is particularly high in patients with drug‐resistant epilepsy, which may be one of the reasons for their susceptibility to recurrent seizures." (PMID 39046369, 2024).
epilepsy (continued). "The signalling pathway in epilepsy may be activated by HMGB1, TLR4, and TLR2, which are considered to increase the level of proinflammatory cytokines." (PMID 39046369, 2024). "After binding to TLR2, TLR4 or RAGE, HMGB1 can trigger the activation of cytokines and affect downstream inflammatory factors that play an important role in modulating neuronal excitability, which can lead to the development of epilepsy." (PMID 39046369, 2024). "In a model of pilocarpine‐induced epilepsy, pharmacological inactivation of anti‐HMGB1 with a monoclonal antibody showed protective effects on neuronal apoptosis by reducing seizure severity and frequency and prevented epileptogenesis caused by the inhibition of HMGB1 release." (PMID 39046369, 2024). "Moreover, we found that the pharmacological effects of GA in neurological diseases or brain injury are closely related to the molecule HMGB1, which accumulated in the serum of epilepsy model mice but down-regulated after GA administration." (PMID 38771510, 2024). "A similar pattern of HMGB1 translocation and subsequent extracellular release in neurons was also observed in conditions such as intracerebral hemorrhage, fluid percussion-induced traumatic injury, and drug-induced epilepsy." (PMID 38892076, 2024). "In addition to elevated levels of HMGB1 in the brain, high levels of HMGB1 in the serum were also observed in epilepsy patients." (PMID 39046369, 2024). "HMGB1, a member of the damage-associated molecular patterns family, is upregulated in experimental epilepsy models and interacts with TLR4 receptors, contributing to epilepsy pathophysiology." (PMID 38792602, 2024). "A clinical study showed that HMGB1 levels are proportional to the severity of epilepsy and that high HMGB1 levels may represent an increased likelihood of antiepileptic drug resistance." (PMID 39046369, 2024). "HMGB1 may be a potential clinical biomarker for prediction, diagnosing, and prognosing of seizures or drug-resistant epilepsy." (PMID 38187384, 2023). "However, this study reported that the CSF HMGB1 concentrations were significantly higher in the drug-refractory epilepsy and newly diagnosed epilepsy groups compared with the other non-inflammatory neurological disorders group." (PMID 37834053, 2023). "Additionally, inflachromene had an anti-seizure potential as a small molecule HMGB-1 inhibitor, as was shown in different animal models of epilepsy." (PMID 37583518, 2023). "They further concluded that HMGB1 might be the main contributor to seizure mechanisms and that CSF HMGB1 can be used as a predictive marker in epilepsy." (PMID 37239204, 2023). "High-mobility group box-1 (HMGB-1) has been widely recognised as a biomarker of epilepsy." (PMID 37239204, 2023). "Some of the approaches may include targeting HMGB1, which seems to exacerbate inflammation in epilepsy." (PMID 37239204, 2023). "Evidence from preclinical studies shows that animal models exposed to lipopolysaccharide (LPS)-induced inflammatory response develop seizure due to pronounced levels of pro-inflammatory cytokines, such as IL-1β, TNF-α, and HMGB1, as seen in epilepsy comorbidities." (PMID 37239204, 2023). "Another mechanism by which HMGB1 may promote epilepsy is by the destruction of the blood–brain barrier." (PMID 35837232, 2022). "Therefore, anti-HMGB1 mAb that significantly blockade the HMGB1 is potential treatment for epilepsy and assessing the efficacies with several experiments of epilepsy models needed to be the objectives for future research." (PMID 36310854, 2022). "Recently, the role of HMGB1 in epilepsy has gradually attracted researchers’ attention." (PMID 35720723, 2022). "An increase in HMGB1 inflammatory subtypes persisted during active epilepsy in these animals." (PMID 35837232, 2022). "Glial activation plays an important role in the development of epilepsy, and HMGB1 may mediate microglial activation during epileptic seizures through the TLR4/NF-κB signaling pathway." (PMID 36388178, 2022).